RNU6-476P (RNA, U6 small nuclear 476, pseudogene)
Gene: Small nuclear RNA gene on chromosome 22 (41,679,711 to 41,679,817, forward strand). Ensembl gene ENSG00000207457.
Homologues: Orthologues: chimpanzee U6 (100% identical), macaque U6 (97% identical). Paralogues in human: RNU6-20P (94% identical), RNU6-25P (93% identical), RNU6-33P (93% identical), RNU6-38P (93% identical), RNU6-1 (93% identical), RNU6-2 (93% identical), RNU6-3P (93% identical), RNU6-48P (93% identical), RNU6-4P (93% identical), RNU6-5P (93% identical), RNU6-6P (93% identical), RNU6-9 (93% identical), and 1288 more.